IL6 (interleukin 6)
Diseases named in the same sentence as IL6 in open-access papers (continued):
Sharing a sentence is not in itself a finding about the gene and the disease.
cystic fibrosis (49 papers, 2005 to 2026). Autosomal recessive disorder caused by pathogenic variants in the CFTR gene (cystic fibrosis transmembrane conductance regulator), which encodes a chloride and bicarbonate channel expressed in epithelial cells, and follow the diagnosis criteria. "Depending on the pattern of ACE2 expression, the SARS-CoV-2 spike (S) protein induced high levels of Interleukin 6 in healthy donor-derived primary airway epithelial cells, but a very weak response in primary Cystic Fibrosis cells." (PMID 36627352, 2023). "A randomized controlled trial revealed that vitamin D deficiency is common in patients with cystic fibrosis, and high-dose vitamin D therapy can help regulate the inflammatory response of CF by reducing levels of the inflammatory cytokines TNF-a and IL-6." (PMID 37612740, 2023). "HE4 was reported to positively regulate inflammatory cytokines including IL-6 in cystic fibrosis, which supported our result to some extent." (PMID 35550579, 2022). "Inhibition of miR-146a in LPS-stimulated cystic fibrosis macrophages increased IL-6 production, and m iR-146a overexpression in human retinal endothelial cells reduced IL-6 expression." (PMID 34564316, 2021). "The ability of LPS isolated from A. baumannii 1053 (a clinical isolate from a patient with cystic fibrosis), to induce cytokine production (e.g., IL-6 and TNF), is similar to that of LPS isolated from E. coli O130 in murine bone marrow-derived macrophages." (PMID 28757686, 2017). "Our data extends previous findings using cystic fibrosis tracheobronchial epithelial cells indicating that IL-8 secretion was greater than IL-6 secretion (basally and after stimulation)." (PMID 22412951, 2012). "In many model systems, cystic fibrosis phenotype airway epithelial cells in culture respond to P. aeruginosa with greater interleukin (IL)-8 and IL-6 secretion than matched controls." (PMID 16008840, 2005). "The predominance of IL-1β mirrors what has been reported clinically using respiratory isolates of Pa isolated during the early stages of Pa infections from patients with cystic fibrosis, whereas the increase in IL-6 and TNF-α has parallels to what was seen in chronic Pa infections." (PMID 38792820, 2024). "Furthermore, there is evidence from a study that the suppression of miR-146a in cystic fibrosis macrophages increases IL-6 production, indicating that miR-146a is functional." (PMID 36140712, 2022). "Additionally, we observed a deep downregulation of hsa-miR-146a-3p, involved in several autoimmune and inflammatory diseases such as cystic fibrosis, where it controls the IL-6 production, contributing to the restriction of the inflammatory response." (PMID 35130828, 2022). "In pediatric cystic fibrosis patients, chemerin levels were comparable to healthy controls and did not correlate with nutritional status and levels of interleukin-1 beta (IL-1b), interleukin-6 (IL-6) and TNF α." (PMID 35327393, 2022). "In addition, miR-199a-5p, another miRNA found to be downregulated in HIV+/TB+, was demonstrated to have a positive relationship with TLR-4 signaling and IL-6 expression in macrophages in a cystic fibrosis model." (PMID 35295678, 2021). "Furthermore, cystic fibrosis patients have increased NE activity with elevated levels of pro-inflammatory cytokines IL-1β, IL-6, IL-8." (PMID 34869231, 2021). "Indeed, IL-6 levels have been reported to be increased markedly in cystic fibrosis patients when the disease exacerbates." (PMID 30887082, 2019). "Studies on cystic fibrosis revealed that the levels of proinflammatory cytokines including IL-1, TNF, IL-6 and IL-8 are higher in CF patients while level of IL-10 is lower comparing to healthy individuals." (PMID 35139898, 2022). "We also considered IL-6, a marker whose production is rather reduced in COPD and cystic fibrosis in response to PAMPs." (PMID 36503361, 2022).
cystic fibrosis (continued). "The relevance of our finding to human disease is demonstrated by the finding that IL-6 is elevated in BAL fluid from the lungs of humans not colonized with bacteria who have non-cystic fibrosis (non-CF) bronchiectasis compared to healthy controls." (PMID 36505420, 2022). "In addition, estrogen has been shown to aggravates inflammation in pseudomonas aeruginosa pneumonia in cystic fibrosis mice via increasing the total white blood cell counts and neutrophils, Th1 cytokines (TNF-α and IL-6) Th2 cytokines (IL-5) and extaxin." (PMID 22563373, 2012). "Therefore, this study aims to analyze the expression of messenger ribonucleic acid (mRNA) for IL-4, IL-5, IL-6, IL-8, GM-CSF, and INF-γ in patients with cystic fibrosis and control subjects through reverse transcription polymerase chain reaction (RT-PCR)." (PMID 20339685, 2010). "This bacteria is reported to enhance inflammation by increasing the production of cytokines such as IL-6, TNF-α, and G-CSF as seen in the case of cystic fibrosis." (PMID 35579429, 2022).
candidiasis (48 papers, 2010 to 2026). Infection with the organism Candida. "The autosomal dominant form is most commonly associated with pathogenic variants in STAT3 that impair Th17/IL-1, predisposing to Staphylococcus aureus and Candida infections, with dysregulated IL-6/IL-10 contributing to eczema-like lesions." (PMID 41378312, 2026). "We theorize that as emapalumab blocks IFNγ, subsequently blocking neutrophil activation and IL-6 modulation; it led to our patient being more susceptible to systemic candidiasis, resulting in fungal emboli that led to her intraparenchymal hemorrhage)." (PMID 40407638, 2025). "IL-6 is a pleiotropic cytokine and fundamental during murine protection against systemic candidiasis caused by C. albicans." (PMID 39037263, 2024). "Experimental studies performed on mice deficient in interleukin-6 have demonstrated the role of this interleukin in the defense against Candida infections." (PMID 37887216, 2023). "A trial assessing the susceptibility of candidiasis in IL-6 deficient mice found that IL-6 deficient mice had increased mortality and higher candida fungal loads when compared to control mice." (PMID 34940403, 2021). "The IL-17A and IL-6 cytokines are specifically induced in the patients after Candida infection, making them a potential target for diagnostic purposes." (PMID 34684298, 2021). "The cytokine IL-6 was induced in wild-type mice in response to Candida infection but was significantly reduced in NLRC4 deficient mice and completely abrogated in NLRP3 and ASC deficient mice." (PMID 22174673, 2011). "In animal studies, interleukin-6 deficiency has been reported to cause Candida infections." (PMID 36340438, 2022). "Macrophage-derived proinflammatory cytokines such as TNFα, IL-1, KC, or IL-6 activate the recruitment, phagocytosis, and killing of fungi, and mice deficient in these cytokines are more susceptible to systemic candidiasis (Basu and others 2008; Gorjestani and others 2012)." (PMID 27046240, 2016). "Macrophage-derived proinflammatory cytokines like IL-1, KC, or IL-6 activate the recruitment of phagocytes and the phagocytosis and killing of fungi by phagocytes, and mice deficient in these cytokines have an increased susceptibility to systemic candidiasis." (PMID 24343653, 2014). "Smokers are seven times more likely to have oral Candida infections, partly due to reduced IL-1β, IL-6, and TNF-α responses and nicotine’s enhancement of CA biofilm formation and adhesion." (PMID 41009855, 2025). "In that study, candidiasis was confirmed in 53% of the patients on hemodialysis, in addition to which hsCRP and IL-6 were elevated, while HDL was significantly lowered." (PMID 40430249, 2025). "IL-6 and IL-1β, both inflammatory cytokines, play a crucial role in inflammation in Candida infections." (PMID 39062060, 2024). "Other cytokines such as TNF-α, IL-6, and GM-CSF are also involved in neutrophil recruitment during candidiasis." (PMID 38787374, 2024). "Here, we utilized an in-vivo candidiasis mice model and employed tocilizumab to curb early IL-6 flare, which has been observed by some." (PMID 34436195, 2021). "While IL-6 is required for Th17 development and resistance to Candida infection, our data show that elevated levels of IL-6 are strongly associated with Foxp3+ TregDys phenotype and immunopathology in infected aged mice." (PMID 33240286, 2020). "Other studies on mice infected with Candida albicans have suggested that IL-6 is fundamental for protection against candidiasis." (PMID 33322794, 2020). "TNF-α and IL-6 participate in the innate immune response against Candida infection by promoting neutrophils production and activation." (PMID 27708385, 2016). "C. albicans infection is associated with increased levels of pro inflammatory monocyte derived cytokines such as TNFα, IL-1, and IL-6 as well as high IL-10, which contribute to the suppression of immunity against candidiasis." (PMID 23144764, 2012).
candidiasis (continued). "Even though DCs isolated from patients with candidosis demonstrate reduced maturation, they do have the ability to produce IL-23 and IL-6, which seemingly can play a direct role in the maintenance of Th17 responses." (PMID 20981280, 2011). "Children with candidiasis showed significantly elevated salivary concentrations of IL-1β (34.5 ± 9.1 vs. 15.2 ± 5.8 pg/mL; p < 0.001), IL-6 (28.9 ± 8.3 vs. 12.4 ± 4.9 pg/mL; p < 0.001), TNF-α (36.8 ± 10.2 vs. 18.7 ± 6.2 pg/mL; p < 0.001), and IL-8 (41.5 ± 11.5 vs. 22.1 ± 7.3 pg/mL; p < 0.001)." (PMID 41301927, 2025). "Mice lacking the ability to produce and release G-CSF and IL-6 have been found to be more susceptible to Candida infections, for example." (PMID 36466340, 2022). "The IL-17 pathway regulates immunity in candida infection, probably via upregulation of proinflammatory cytokines (IL-6 and neutrophil-recruiting chemokines) among other actions, and the use of IL-17 inhibitors have was associated with an increased risk of mucocutaneous candidiasis." (PMID 35843765, 2022). "However, WT and Gsdmd-/- macrophages generated the same amount of TNFα and IL-6 after Candida infection, supporting the notion that the expression and secretion of these cytokines were GSDMD-independent." (PMID 34795266, 2021). "Candida infection also directly triggered TNFα and IL-6 production in macrophages." (PMID 34795266, 2021). "Collectively, these results show that tongue immunopathology could be ascribed to an impairment of IL-1β and excessive production of IL-6 during oral Candida infection in aged mice." (PMID 33240286, 2020). "Our results imply that Candida infection in the context of IL-1β/IL-6 imbalance may lead to an inappropriate accrual of dysfunctional IFN-γ+Foxp3+ cells." (PMID 33240286, 2020). "Thus, our study supports that IL-1β/IL-6 imbalance is central to Foxp3+ cell plasticity and inflammation control during Candida infection." (PMID 33240286, 2020). "Although Th17 cells are also important for activation of inflammation and recruitment of neutrophils in candidiasis, we did not observe the changes in Th17 population and IL-6 cytokines that is the traditional hallmark of Th17 proliferation." (PMID 25381480, 2015). "The importance of IL-6 to the immune response to candidiasis has been noted previously." (PMID 23144764, 2012). "Recently, studies have shown that IL-23 may indeed play a key role in controlling vaginal candidosis, with the IL-23 cytokine, together with IL-6 readily detected in vaginal secretions of infected women." (PMID 20981280, 2011). "Although mice deficient in IL-6 (Il-6-/-) have no apparent deficit in neutrophil number during the basal state, they displayed reduced neutrophilia and neutrophil response during Listeria and Candida infections." (PMID 36148240, 2022). "Of the cytokines induced, IL-1α, IL-1β, IL-6, IL-10, IL-17A, IL-18, IFN-γ, and TNF-α have been previously shown to play an important role in the pathogenesis of invasive candidiasis in vivo." (PMID 22916017, 2012). "The IL-6 and CRP values are the most increased in a candida infection." (PMID 40242671, 2025). "Mouse model studies have shown that AMPs can control candidiasis, such as Gomesin, a cationic peptide of 18 amino acids obtained from the caranguejeira spider from Brazil, which protected C. albicans-infected mice and induced pro-inflammatory cytokines such as TNF-α, IFN-ɣ, and IL-6." (PMID 40985427, 2025). "Notably, two (patients T24 and T31) showed remarkably high IL‐17A‐ and IL‐17F‐binding and had candidiasis; nevertheless, these antibodies cannot be a strong predisposing factor, as two other patients with CMC and five with intercurrent Candida infections tested negative against IL‐6." (PMID 27957331, 2016). "Ocular concentrations of IL-6, CXCL1/KC, CXCL2/MIP-2, and CCL2/MCP-1 were significantly elevated during C. albicans infection compared with non-albicans Candida infection by the reference strains." (PMID 30386320, 2018).
cardiac arrest (48 papers, 2010 to 2025). Cessation of breathing and/or cardiac function. "Serum IL-6 levels are differentially associated with systemic inflammation or neuronal injury, depending on the severity of the cardiac arrest." (PMID 39199472, 2024). "We investigated the time-course of changes in IL-6 and its association with other markers (systemic inflammation and myocardial and neuronal injury), according to the injury severity of the cardiac arrest." (PMID 39199472, 2024). "IL-6 has been found to be involved in e.g., tissue hypoxia after cardiac arrest and has been shown to be independently associated with poor outcomes in unconscious out-of-hospital cardiac-arrest patients." (PMID 37790622, 2023). "After out-of-hospital cardiac arrest IL-6 is elevated and particularly associated with 30-day mortality." (PMID 35711345, 2022). "A post hoc analysis of data from the TTM1 trial demonstrated significant IL6 elevation 24 h after cardiac arrest and a significant association between higher IL6 levels and greater severity of PCAS in both temperature groups (33 °C and 36 °C)." (PMID 34920723, 2021). "We and others have previously reported that increased IL-6 levels measured after cardiac arrest are associated with increased mortality and worse neurological outcome." (PMID 27038920, 2016). "In addition, the independent association of IL-6 with other biomarkers revealed variability in the severity of the cardiac arrest." (PMID 39199472, 2024). "Similarly, cytokines such as IL-6 and IL-8 are associated with poor neurological outcomes in individuals who experienced cardiac arrest." (PMID 37746258, 2023). "However, cytokine levels such as IL-6 vary greatly depending on the timing of blood withdrawal and the underlying condition that leads to cardiac arrest." (PMID 36555922, 2022). "IL-6 plays a key role as it is associated with leukocytes, vascular endothelium and parenchymal cells and is associated with unfavorable outcome even after cardiac arrest." (PMID 35711345, 2022). "Therefore, we hypothesized that IL-6 levels are heterogeneously associated with the severity of the cardiac arrest injury." (PMID 39199472, 2024). "Therefore, this anti-inflammatory myokine, IL-6, may alleviate the risk of neurological injury arising from aggressive inflammatory insults after cardiac arrest." (PMID 33379208, 2020). "A difference was only observed for IL-6, which decreased in Fingolimod vs Control (e.g., 5.6 ± 4.8 vs 59.4 ± 20.6 pg/ml at 2 h after cardiac arrest, respectively; p = 0.126)." (PMID 38954057, 2024). "The available data suggest that IL-6 is a potential target to mitigate secondary brain injury after cardiac arrest." (PMID 39199472, 2024). "As anticipated, the time-course of IL-6 levels exhibited distinctions by the injury severity of the cardiac arrest, as estimated using the following well-validated scoring system: the rCAST grading system (low vs. moderate vs. high severity)." (PMID 39199472, 2024). "Significantly lower IL-6 levels manifest in patients with low-severity cardiac arrest than in those with moderate- or high-severity cardiac arrest." (PMID 39199472, 2024). "Thus, this study aimed to investigate the association of IL-6 with the severity of cardiac arrest and the independent relationship between IL-6 and other biomarkers of systemic inflammation and myocardial or neuronal injury for each severity level of cardiac arrest." (PMID 39199472, 2024). "IL-6 and TNFα expression have been found to be involved in inflammation due to tissue hypoxia after cardiac arrest." (PMID 37790622, 2023). "The most recent approach is inhibiting IL-6 using tocilizumab, a monoclonal antibody against IL-6, in a post-cardiac arrest setting." (PMID 35711345, 2022). "Inflammatory cytokines, such as IL-6, IL-10, and TNF-α, have been associated with cardiovascular dysfunction in patients with cardiac arrest." (PMID 33510459, 2021).